OPA1 (OPA1 mitochondrial dynamin like GTPase)
Diseases named in the same sentence as OPA1 in open-access papers (continued):
Sharing a sentence is not in itself a finding about the gene and the disease.
tumor (continued). "We performed a Western blot analysis on protein extracts from enriched CD45-negative tumor cells to monitor the expression of OMA1, OPA1, and DELE1 isoforms involved in the handling of mitochondrial and ER stress, respectively." (PMID 37024121, 2023). "Accordingly, lower levels of DDR1, MFN2 and OPA1 and higher levels of pAMPK were detected in WM983B and A375M2 tumours, compared to WM983A and A375P tumours as shown in vitro." (PMID 37217519, 2023). "We identified that OPA1, MFN1, and DNM1L were significantly increased in both NSCLC tumor tissues (P < 0.05)." (PMID 36573240, 2022). "By using a multipronged approach, we substantiate that OPA1 inhibition curtails TNBC growth in vitro and in vivo, by counteracting tumor growth, invasiveness, and neovascularization." (PMID 35279198, 2022). "Genes and proteins regulating the TCA cycle (PDHA1, SUCLG2, SUCLG1, and IDH2) as well as mitochondrial function (VDAC1, MRPS31, LARS2, OPA1, and MTIF2) showed higher transcripts and protein levels in Wnt‐high compared with Wnt‐low tumor entities." (PMID 35904277, 2022). "Knockdown of the other two mitochondrial fusion regulatory genes OPA1 or MFN1 attenuates OXPHOS and ATP production of tumor cells." (PMID 35413941, 2022). "Overall, this study indicates that celastrol inhibits tumor angiogenesis by suppressing mitochondrial function and morphology via the STAT3/OPA1/P65 pathway and provides new insight for mitochondrion-targeted cancer therapy." (PMID 36678677, 2022). "To understand what drives reduced tumor burden in KPO mice, we explored the consequences of Opa1 deletion in vitro using a KPO tumor cell line that retained both Opa1FL alleles and thus is initially functionally KP." (PMID 36516772, 2022). "Expression of Tomm20 and MT-ND1 was reduced in the tibialis anterior muscle of tumour-bearing mice, while the expression of COXIV and OPA1 was reduced in the gastrocnemius muscle of tumour-bearing mice." (PMID 33975599, 2021). "The knockdown of the fusion regulator genes, OPA1 (Optic atrophy 1) or MFN1 (Mitofusin 1), inhibited the fusion process in HCC cell lines and CCA tumor organoids." (PMID 31947947, 2020). "Western blotting evaluation of HCC samples and matched non-tumor tissue samples demonstrates that OPA1 expression is decreased in up to 40% of HCC patients, suggesting important roles for OPA1 in the development of HCC." (PMID 32373606, 2020). "In the present study, we did not observe any beneficial effect associated with inhibition of ACVR2B on the expression of down‐regulated mitochondrial proteins including OPA1, PGC1α, and VDAC in tumour hosts." (PMID 33200567, 2020). "By genetic knockdown of the key fusion regulators OPA1 or MFN1, we inhibited mitochondrial fusion in HCC cell lines and CCA tumor organoids." (PMID 31947947, 2020). "Analysis of the Oncomine online database, containing five cohorts of HCC patients, revealed that both OPA1 and MFN1 are more highly expressed in HCC tumor tissue compared to liver tissue in the majority of cohorts." (PMID 31947947, 2020). "The mitochondrial dynamics and structure depend essentially on optic atrophy 1 protein (OPA1) and dynamin-related protein 1 (DRP1) proteins, influencing several cellular processes in tumor cells such as apoptosis." (PMID 31547300, 2019). "Fusion-related (OPA1, MFN1) as well as fission related (DNM1L) genes were found to be increased in the basal-like subtype when compared to Luminal A tumor samples." (PMID 31231612, 2019). "Pushing the network away from fusion using the OPA1 inhibitor MYLS22 reduces mitochondrial membrane potential, perturbs MM-MSC glycolysis/OXPHOS coupling, and lowers mitochondrial ROS compared to the normal donor MSCs, weakening their pro-tumor support." (PMID 41146909, 2025). "At the end of the experiment, the tumor volumes and weights in the sh-METTL3 group were significantly lower than those measured in the sh-control group, and these effects were reversed by overexpression of RRM2B or OPA1." (PMID 38549713, 2024).
tumor (continued). "Knockdown of OPA1 or MFN1 to inhibit mitochondrial fusion weakened oxygen consumption and cellular ATP production of tumor cells, suppressed cell growth in vitro, and inhibited tumor formation in vivo." (PMID 38812059, 2024). "Additionally, silencing of OPA1 or MFN1 decreased mitochondrial fusion in HCC cells and tumor organoids of cholangiocarcinoma, resulting in cell apoptosis in vitro and tumor growth after tumor cell engraftment in nude mice." (PMID 38299199, 2024). "Mechanistically, while Opa1 silencing did not affect mitochondrial respiration, it upregulated the tumor suppressors of the miR-148/152 family." (PMID 36827549, 2023). "In line with the high OPA1 in CSCs, SPDEF was expressed at a higher level in tumor spheres." (PMID 36809297, 2023). "Although Drp1 deletion does not rescue in vivo tumor growth following Opa1 deletion, we isolated multiple KPDO tumor cell lines with complete in vivo deletion of both Opa1 and Drp1, but not a single KPO cell line that completely deleted Opa1 in vivo." (PMID 36516772, 2022). "Also, the proportion of OPA1 and MFN1 in various cells tend to be more distributed in tumor epithelial cells." (PMID 36573240, 2022). "Mechanistically, while OPA1 silencing did not reduce mitochondrial respiration, it increased levels of miRNAs of the 148/152 family known to inhibit tumor growth and invasiveness." (PMID 35279198, 2022). "Together, these data suggest that Opa1 deletion does not inhibit tumor growth by inducing apoptosis or through inhibition of mitochondrial fusion." (PMID 36516772, 2022). "Further, inactivation of mitochondrial fission permits Opa1-null tumor cell line isolation but not in vivo tumor development." (PMID 36516772, 2022). "In this study, we revealed that knockdown of OPA1 failed to maintain a balance of mitochondrial dynamics and further enhanced the sensitivity of tumor epithelial cells to immune cells." (PMID 36573240, 2022). "To assess how Opa1 deletion affects ETC function and cristae homeostasis in the presence and absence of Drp1, we used KPO and KPDO tumor cells that delete retained floxed alleles following in vitro AdCre infection." (PMID 36516772, 2022). "We speculate that tumors with Opa1 and Drp1 deletion undergo initiation, but that ETC dysfunction from combined chronic Drp1 deletion and accumulation of fission-independent cristae disruptions unrepaired by Opa1 inhibit tumor progression." (PMID 36516772, 2022). "Surprisingly, simultaneous deletion of Opa1 and Drp1 does not rescue tumor development." (PMID 36516772, 2022). "Interestingly, it was found that OPA1 and MFN1 were strongly correlated in tumor epithelial cells." (PMID 36573240, 2022). "This apparent discrepancy may reflect tumor cells’ adaptive response to specific tumor microenvironmental conditions that might not be related to Opa1’s fusion activity." (PMID 25822260, 2015). "However, this should not be equated to naturally OPA1 low-expressing tumor cells." (PMID 36573240, 2022). "Further, Drp1 deletion rescues the effects of Opa1 deletion on in vitro colony formation and ETC function but not in vivo tumor growth." (PMID 36516772, 2022). "When Comparing the CAR-T cells in the presence or absence of tumor cells, we noticed that OPA1 and CPT1 were the only two markers downregulated in 28z/IL-7-CAR-T cells in the presence of tumor cells." (PMID 35869100, 2022). "We measured by qPCR the mRNA levels of Exon4b-containing OPA1 isoforms (i.e., isoforms 3, 5, 6, and 8) and those without Exon4b (i.e., isoforms 1, 2, 4, and 7) in 22 paired HCC and adjacent non-tumor liver tissues." (PMID 32373606, 2020).
cancer (33 papers, 2009 to 2026). A tumor composed of atypical neoplastic, often pleomorphic cells that invade other tissues. "Studies have indicated that OPA1 is overexpressed or mutated across various cancers and is closely associated with protein phosphorylation, patient prognosis, and immune cell infiltration." (PMID 38911373, 2024). "As we suspected, the results showed a significant correlation between high OPA1 expression in tumors and high infiltration levels of cancer-associated fibroblasts." (PMID 37980164, 2023). "High expression of Mfn1, Mfn2 and OPA1 has also been linked to cancer cell proliferation, survival and invasion, while their inhibition blocks cell growth and triggers apoptosis of different cancer cells." (PMID 32244541, 2020). "Presently, the correlation between chemoresistance and mitochondrial dynamic proteins has been shown that OPA1 loss-induced mitochondrial fragmentation tends to cause an increase in resistance to drug treatments in cancers." (PMID 30674338, 2019). "Furthermore, the S158N polymorphism within OPA1's exon 4 exhibiting attenuated fatty acid release from LDs is associated with changes in metabolic traits in pediatric cancer survivors." (PMID 42182382, 2026). "Upregulated mitochondrial fusion machinery, such as OPA1, is observed in cancer cells of various origins and might be associated with worse prognosis." (PMID 33152171, 2021). "Considering the essential roles of Exon4b on mitochondrial function including energetics, we tested whether the compromised mitochondrial respiration observed in some cancer cells could be associated with OPA1-Exon4b." (PMID 32373606, 2020). "Therefore, we will explore the level of OPA1 gene expression in pan-cancer, its mutation types, and the relationship of these alterations with patient prognosis and immune microenvironment, as well as the molecular mechanisms that may be involved." (PMID 37980164, 2023). "Collectively, m6A promoted mitochondria fusion via induction of GSH synthesis and OPA1 expression, which facilitated cancer cell growth and CRC development." (PMID 38549713, 2024). "OPA1 overexpression can also increase glycolytic activity to enable cancer cells in LUAD patients to achieve immune escape." (PMID 37980164, 2023). "In sum, MYLS22 appears as a powerful pro-death compound that can be used alone or in combination with targeted therapeutics in conditions where Opa1 mechanistically participates in the emergence of chemoresistant cancer cells." (PMID 37019897, 2023). "In pancreatic ductal adenocarcinoma (PDAC), the presence of cancer stem cells (CSCs) was associated with high invasiveness of PDAC, while OPA1 overexpression was found in CSCs and has a regulatory effect on tumorsphere formation." (PMID 37980164, 2023). "Here, we used the TIMER tool to analyze relevant data from the TCGA database to explore the statistical relationship between OPA1 expression levels and the level of immune cell infiltration in pan-cancer." (PMID 37980164, 2023). "First, in addition to its core function in mitochondrial fusion, OPA1 regulates several hallmarks of cancer: cytochrome c release and apoptosis, mitochondrial respiration, cell proliferation and angiogenesis." (PMID 35279198, 2022). "Among these, OPA1 has been identified as a prognosis-related gene in several cancers, and its expression at high levels has been found to correlate with a worse prognosis in PDAC patients." (PMID 35565283, 2022). "We therefore measured the consequence of OPA1 downregulation on key facets of cancer cell biology in MDA-MB-231, a TNBC cell line." (PMID 35279198, 2022). "It has been reported that mitochondrial fission is frequently increased in cancer cells due to the downregulation of the mitofusin proteins including Mfn1, Mfn2, and Opa1 and/or the upregulation of Drp1." (PMID 35582383, 2021). "Given the crucial role of OPA1 in the regulation of mitochondrial morphology and function, several studies focused on the relevance of its activity in cancer." (PMID 33233365, 2020).
cancer (continued). "The authors well-characterized a mutually exclusive mechanism in which SOX2 blunted OPA1 expression levels in this type of cancer." (PMID 33233365, 2020). "As a result, we identified eight common mutated genes (EBAG9, MTDH, ATP6V1C1, OPA1, ATCL6A, BCL6, SENP5, KRAS) in the three different cancer types and used them as cross-cancer biomarkers to perform an integrative network analysis." (PMID 29459674, 2018). "Both PABPC1 and OPA1 are aberrantly expressed in many cancers and are known to promote tumorigenesis and progression, thereby serving as promising candidates to target in RBness cancers." (PMID 40138429, 2025). "The expression level of OPA1 may play a very important role in the occurrence and development of pan-cancer." (PMID 37980164, 2023). "Second, OPA1 is often amplified across pan-cancer genomic datasets, including breast." (PMID 35279198, 2022). "We believe that our study nominates OPA1 as a potential target in cancer therapy." (PMID 35279198, 2022). "We also assessed the role of OPA1-Exon4b in mitochondrial bioenergetics of cancer cells." (PMID 32373606, 2020). "Since Opa1 processing complicates its function in maintenance of mitochondrial metabolism, future studies are required to focus more on the distinct regulatory machinery of Opa1 and its processing involved in mitochondrial metabolism within various cancer cells." (PMID 31551926, 2019). "We show, for the first time, the presence of the CTF fragment of OPA1 in cancer tissue, and this might represent a metabolic adaptation of mitochondria to sustain cancer cell growth." (PMID 31547300, 2019). "In various forms of cancer, Opa1 is highly expressed and indicates poor prognosis." (PMID 28402939, 2017). "Furthermore, mitochondrial morphology was not affected, but loss of prohibitins did lead to the degradation of the fusion protein OPA1 and, in certain cancer cell lines, to a reduced capability to exhibit anchorage-independent growth." (PMID 20856874, 2010). "The results indicate that OPA1/3 may be an effective prognostic biomarker and are closely related to immune mechanisms, illustrating its potential as an immunotherapeutic agent for a variety of cancers." (PMID 38911373, 2024). "Our prognostic analysis results have shown that the expression level of OPA1 is significantly correlated with the prognosis of cancer patients, so we speculate that OPA1 may affect the prognosis of patients by affecting the infiltration level of cancer-associated fibroblasts." (PMID 37980164, 2023). "To explore the hypothesis that dysregulated mitochondrial dynamics may impact drug sensitivity, we began by examining the alteration status of six canonical dynamics-regulating genes - OPA1, MFN1, MFN2, FIS1, MFF, and DNM1L (which encodes Drp1)—in human cancers." (PMID 29700304, 2018). "In particular, reduced protein expression levels of Mfn1, Mfn2, and Opa1 and high levels of Fis1 and DLP1/ Drp1 were observed in certain cancer conditions." (PMID 28402939, 2017). "Because also mitochondrial fusion genes appear to be amplified in the same cancers, we wished to investigate whether levels of the three fusion mediators OPA1, MFN1 and MFN2 were upregulated across cancer types." (PMID 35279198, 2022). "However, our literature search revealed that there is no article on the pan-cancer analysis of OPA1, so a comprehensive analysis of OPA1 in tumors is necessary." (PMID 37980164, 2023). "Thus, in PC9M2 cells total mitochondrial content is not changed, but Opa1 is specifically upregulated, a feature that is shared with several other conditions of cancer cell resistance to chemotherapy and targeted therapeutics." (PMID 37019897, 2023). "Furthermore, OPA1 silencing reduced cell proliferation, invasion and adhesion on fibronectin, an extracellular matrix protein typical of the cancer niche without affecting cellular adhesion on gelatin." (PMID 35279198, 2022).
cancer (continued). "Finally, the increase in cancer prevalence offers a potential explanation as to why animals do not display constitutively high OPA1 levels that are conversely beneficial against adult life cell death." (PMID 26039448, 2015).
mitochondrial disease (24 papers, 2009 to 2024). "One of the therapeutic approaches tried for OPA1-related mitochondrial diseases is genome editing using small ribonucleoprotein particle U1 (U1 snRNP), especially since 30% of OPA1 pathogenic variants are splice-site." (PMID 35736332, 2022). "Three groups of patients with mitochondrial disease were assessed (single large-scale mtDNA deletion and multiple mtDNA deletions due to pathogenic OPA1 and POLG mutations) in single muscle fibers laser captured in transverse and longitudinal sections of muscle biopsies." (PMID 30076399, 2018). "Despite the multifactorial role of OPA1 in mitochondrial health, loss of its function commonly causes autosomal‐dominant optic atrophy and, only under certain conditions, leads to a systemic mitochondrial disease." (PMID 29604226, 2018). "In this connection, modulation of OPA1 levels (and in particular its overexpression) has been previously shown to be beneficial in models of mitochondrial disease, including resistance to apoptosis and enhancement of ETC functionality." (PMID 36367943, 2022). "Together, Opa1v1 or Opa1v1Δ4 mice do not exhibit the mitochondrial dysfunction typically associated with OPA1 mutations observed in human cases, indicating a lack of the characteristic mitochondrial disease manifestations." (PMID 39093974, 2024). "OPA1 has been considered a promising target for the treatment of mitochondrial diseases." (PMID 37200096, 2023). "Thus, except for OPA1, all other DOA genes were initially identified as causing severe, essentially recessive, mitochondrial diseases, while dominant variants in these genes are causing DOA." (PMID 35885985, 2022). "In addition to the two widely-studied mitochondrial proteins OPA1 and MFN2, mutations in SLC25A46 have also been identified as a pathogenic cause in a spectrum of neurological and mitochondrial diseases." (PMID 34945750, 2021). "Similarly, OPA1-overexpression can reverse motor and respiratory deficits and increase lifespan in mouse models of mitochondrial disease, with OPA1 being important for regulating cristae structure, stabilising OXPHOS complexes and ameliorating cell death." (PMID 32714603, 2020). "However, there are some reports that the overexpression of Opa1 ameliorates the phenotype of mitochondrial disease models while the inhibition of Drp1-mediated mitochondrial fission improves mitochondrial dynamics and bioenergetics, stimulating neurogenesis." (PMID 33264289, 2020). "Notably, mutations in SPG7 (≈4/100,000) and PEO1 (≈3/100,000), followed by OPA1 (≈1/100,000) and RRM2B (≈0.9/100,000) have emerged as major causes of adult mitochondrial disease." (PMID 25652200, 2015). "Thus, increasing OPA1 levels by targeting or inhibiting MTFR1L may represent a potential unexplored therapeutic target for mitochondrial diseases." (PMID 36367943, 2022). "Collectively, these results strongly suggest that DNJ is effective in increasing oligomer levels of OPA1, rescuing mitochondrial function in HCM iPSC-CMs, and presents the potential for extended and broader clinical use of DNJ in other mitochondrial disease models." (PMID 37200096, 2023).